PIM1 (Pim-1 proto-oncogene, serine/threonine kinase)
Diseases named in the same sentence as PIM1 in open-access papers (continued):
Sharing a sentence is not in itself a finding about the gene and the disease.
cancer (continued). "PIM1 is a known oncogene, upregulated in GBM and in several other cancers where it contributes to recurrence and drug resistance; however, its specific involvement in MNG is, to date, unknown." (PMID 40943185, 2025). "The PIM1 substrates we identified were involved in a variety of oncogenic processes, and included N-Myc Downstream-Regulated Gene 1 (NDRG1), which has reported roles in suppressing cancer cell invasion and metastasis." (PMID 33398037, 2021). "The IC50 of SMI-4a but not SGI-1776 was inversely associated with Pim1 protein expression, indicating that the specific inhibition of Pim1 by SGI-1776 is not the sole mechanism for its anti-cancer activities." (PMID 34267653, 2021). "However, data from other cancers indicate that NEK2 and PIM1 kinases possess oncogenic potential and that they interact with diverse downstream signaling pathways." (PMID 32504181, 2020). "Moreover, the C‐dots disrupt likely through nucleotide excision DNA repair at low dose during DNA ligation step suggesting the antimicrobial effect and targeting Pim‐1, EGFR, mTOR, and DNA damage pathways in cancer cells." (PMID 31692950, 2019). "Although PIM1 is a known oncogene in various human cancers, its potential role as a therapeutic target has not been explored in SACC." (PMID 29467592, 2018). "Over-expression of PIM1 and PIM2 kinases has been reported in hematologic malignancies also in solid tumors such as diffuse large B cell lymphomas (DLBCL) and prostate cancer, thus, these findings make it an attractive target for cancer therapy." (PMID 29564572, 2018). "In agreement with the role of FGFR1 in promoting cell proliferation and carcinogenesis, a number of iFGFR1-upregulated genes are cancer-driving genes such as ETS1, PIM1, NRG1, MMP1, and FOXQ1, while some iFGFR1-downregulated genes are tumor suppressors such as NR4A1 and GDF15." (PMID 30111373, 2018). "PIM belongs to a family with three closely related members (PIM-1, PIM-2, and PIM-3), which are constitutively active serine/threonine kinases that promote cell survival, proliferation and migration in several malignancies including cancers." (PMID 28851457, 2017). "Furthermore c-MYC and PIM1 have also been shown to cooperate in prostate tumourigenesis, while the inhibition of PIM kinases in c-MYC-expressing cancers decreases proliferation, survival and tumourigenicity." (PMID 26643319, 2015). "Notable cancer genes with high fractions of hypomutated positions include PIM1 and MED12, with respectively 34% and 32% of their non-coding length that is hypomutated." (PMID 26588488, 2015). "The high level of expression of PIM1 and PIM2 in ABC-DLBCL and the reported synergistic effect of these two kinases with c-MYC in several cancers, prompted us to test the efficiency of the pan-PIM kinase inhibitor AZD1208 in preventing proliferation of aggressive NHL-derived cell lines." (PMID 26643319, 2015). "Furthermore, down-regulation of HSP90AA1 led to the degradation of its client proteins (PIM1 and AKT1), which are also cancer therapy targets." (PMID 25167922, 2014). "In the context of cancer progression, the significance of different subcellular localization patterns of Pim-1 has not been fully elucidated." (PMID 25121590, 2014). "Given the central role of Myc in many cancers, including RCC, inhibition of PIM-1 activity may promote Myc degradation and subsequently decrease tumour cell proliferation." (PMID 22015557, 2011). "To analyze whether PIM1 expression is increased in GBM stem-like cells, we cultured LN-18 as so-called neurospheres which are described to be enriched in cancer stem cells." (PMID 34681783, 2021). "Overall, it has been shown that the rough tumor microenvironment of PDA cancer cells renders them chemoresistant, and in combination with HuR’s posttranscriptional regulation of specific target genes (COX-2, VEGF, c-Myc, WEE1 and PIM1), cell growth and survival are enhanced." (PMID 34572861, 2021).
cancer (continued). "PIM1 is a serine/threonine kinase, the expression of which is controlled by the JAK/STAT pathway, and has also been associated with resistance to chemotherapy and molecularly targeted agents in several cancer types, but to our knowledge not previously for NB." (PMID 31780656, 2019). "Overexpression of PIM-1 has been reported in haematological malignancies and in many solid tumours, which suggests that blocking PIM-1 kinase activity may be a promising approach for cancer therapy." (PMID 22015557, 2011). "Importantly, it has been demonstrated that PIM1 gene expression is induced by IL-6 via the JAK/STAT signaling pathway and that T. vaginalis–induced IL-6 likely provides an additional molecular link between exposure of human PECs to T. vaginalis, stress, and cancer induction." (PMID 22912571, 2012). "In addition, Aid is also reported to generate point mutations and/or double strand breaks at non-Ig locus, for example BCL6, MYC, PIM1 and PAX5, which are related to the cancer genesis." (PMID 24718089, 2014).
tumor (156 papers, 2008 to 2026). "It has been reported that elevated PIM-1 protein levels were associated with increased malignancy and a higher tumor grade." (PMID 40565356, 2025). "This raises the possibility that the other COSMIC PIM1 variants seen in these tumours and predicted to be activating by our method (e.g. p.Gly28Asp, p.Glu135Lys, p.Pro33Ser) also increase its activity." (PMID 41152984, 2025). "MYD88 (73%) was the most common mutation in primary tumor tissues, followed by the mutation of PIM1(64%) and CD79B (55%)." (PMID 40475774, 2025). "The missense and frameshift mutations found in DLBCL due to SHA preserve Pim-1 functionality and tumor cells remain sensitive to PIM447 inhibition." (PMID 36694243, 2023). "Treatment with Pim inhibitors (AZD1208 or TP-3654) in T-ALL or T-LBL patient derived xenograph mice models carrying the TCRβ-PIM1+ translocation or high Pim-1 expression levels caused tumor growth to be substantially inhibited." (PMID 36694243, 2023). "In vitro studies performed with HNSCC cell lines have associated PIM-1 with increased tumor aggressiveness." (PMID 34993612, 2022). "The mechanism underlying tumor repressive properties of myricetin is partly explained by the inhibition of PIM1 and disruption of PIM1/CXCR4 interaction." (PMID 32521759, 2020). "Downstream genes activated by STAT3 have been associated with tumor proliferation and survival, including PIM1/PIM2, MYC, BIRC5 and BCL2L134–39." (PMID 30741931, 2019). "The results revealed that the expression levels of p-Smad2, p-Smad3 and p-c-Myc in the PIM1-deficient tumour edge tissues were significantly lower than those in the control tumour edge tissues." (PMID 29472550, 2018). "It would be of interest to compare the profiles of lymphocyte phenotypes, clonality and determine the presence of recurrent mutations (involving MYD88, CD79B and PIM1 genes) in the tumor, plasma and bone marrow." (PMID 28636991, 2017). "We found that plasma PIM-1 levels were associated with age, tumour location and TNM staging (P = 0.031, P = 0.000 and P = 0.013, respectively)." (PMID 27596051, 2016). "Nevertheless further studies in order to elucidate the exact mechanism of pim-1 action in tumors and tumor associated mucosa, are still warranted." (PMID 24116137, 2013). "Indeed, considering only tumour-derived, confirmed somatic variants the counts are only 11 for PIM1 p.Ser97Asn and six for MAP2K3 p.Ala84Thr." (PMID 41152984, 2025). "We speculate that the utilization of LDs contributes to PIM1-associated resistance to chemotherapy via promoting tumor survival." (PMID 38097734, 2024). "Clinically, elevated PIM1 was associated with high tumor grade." (PMID 30989585, 2019). "In addition, Pim-1 expression in NSCLC tissues was significantly associated with tumor size (P = 0.002), lymph node metastasis (P = 0.026), histological type (P < 0.001) and clinical staging (P = 0.019) in NSCLC patients." (PMID 25342548, 2014). "The results of these analyses indicate that the pim-1 expression in tumor-adjacent mucosa and tumor stroma, as well as PTS were significantly associated with DFS (P<0.0001, P=0.0041, P< 0.0001, respectively) and OS (P<0.0001, P=0.0066, P< 0.0001, respectively)." (PMID 24116137, 2013). "PIM1 overexpression in multiple tumor types is linked to poor prognosis." (PMID 24285958, 2013). "Moreover, we observed that the Pim inhibitor SGI-1776 prevented lipopolysaccharide (LPS)-induced bone loss and tumor-associated osteolysis, which suggests that Pim1 may be a potential therapeutic target for bone resorption-related diseases." (PMID 40164682, 2025). "For example, PIM1 is an ER regulated proto-oncogene that has been shown to play a role in BCa cell proliferation, migration and metastasis and is associated with high grade tumours; KRT13 has been associated with BCa cell growth and metastasis and LOXL4 is an established promoter of cell invasion." (PMID 25488809, 2015). "In addition, pim-1 expression in tumor stroma significantly associated with DFS." (PMID 24116137, 2013).
tumor (continued). "Augmented circular RNA zinc finger with KRAB and SCAN domains 1 (circZKSCAN1) expression facilitated ccRCC development and accelerated tumor progression by targeting the miR-1294/ Pim-1 proto-oncogene, serine/threonine kinase (PIM1) axis." (PMID 40178680, 2025). "In vivo experiments then showed that, when mice with lipopolysaccharide-induced bone loss or tumor-induced osteolysis were treated with SGI-1776, a Pim1 inhibitor that is more selective for Pim1, the bone loss was significantly ameliorated." (PMID 40164682, 2025). "CircRNAs 0076215 and 0076216, both generated from the PIM1 host gene, were predicted to sponge miRNAs 16-5p and 195-5p, two tumor suppressors in MNG, in turn targeting PIM1." (PMID 40943185, 2025). "There are thus good arguments for why increased PIM1 function would be expected in these tumours as either a primary or secondary driver event." (PMID 41152984, 2025). "Regarding the cytotoxicity against tumor cells as well as the ability to inhibition of recombinant CK2/PIM-1 kinases, further investigations of biological action of the most promising compound, i.e., cpd." (PMID 40565356, 2025). "The histology revealed that tumor area was reduced in Pim1−/− mice compared with WT mice, although the reduction was less than that observed with SGI-1776 treatment." (PMID 40164682, 2025). "Specifically, the CXCL1, IFNG, and SERPINE1 in the tumor group had higher expression, while PIM1 and STK40 in the tumor group had lower expression." (PMID 40455337, 2025). "To confirm the GSK3β-PPARα signaling axis downstream of PIM kinase effectively alters LD accumulation in vivo, we assessed tumor tissues (n = 3 tumors/group) by western blotting alongside cell lysates exhibiting PIM1 induction." (PMID 38097734, 2024). "PIM1 promotes tumor progression through various mechanisms, impacting cell cycle progression, proliferation, and survival." (PMID 38097734, 2024). "miRNA-370 was also found to act as a tumor suppressor that targets PIM1 gene expression, thus regulating glycolysis in hepatocellular carcinoma cell lines." (PMID 39372407, 2024). "Immunostaining of tumor tissue sections from lung biopsies showed weak positive signals for PIM1, p-GSK3β (Ser9), and Vimentin before treatment, which subsequently became strong positive signals upon development of acquired osimertinib resistance." (PMID 39227379, 2024). "Pim-1 transgenic mice are also more susceptible to accumulating mutation(s) in response to genotoxic agents’ exposure, as evidenced by an increase in tumor development in Pim-1 transgenic mice exposed to carcinogens or ionizing radiation." (PMID 36694243, 2023). "It was also found that PIM1 can also phosphorylate the pro-apoptotic protein Bad, inactivating it, preventing the apoptosis of tumor cells, and promoting the survival of the cells." (PMID 36871027, 2023). "In vivo smooth muscle invasion assays showed that overexpression of PIM1 significantly increased the depth of tumor cell invasion, and treatment with PIM inhibitors significantly reduced intramuscular PCa invasion." (PMID 37042842, 2023). "PIM1 can enhance the activity of Bcl-2 by phosphorylating B cell lymphoma-2 protein (Bcl-2), thus promoting the proliferation of tumor cells and further promoting the invasion and migration of tumors." (PMID 36871027, 2023). "In patient-derived xenografts harbouring the common activating ALK mutations (F1174L, F1245C), combinatorial ALK (ceritinib) and PIM1 (AZD1208) inhibition displayed greater anti-tumour efficacy than either agent in isolation." (PMID 37414143, 2023). "Across all samples, PIM1 was strongly expressed in tumor cells seeded onto the peritoneal side of the diaphragm and expression was retained in invading cells." (PMID 37042842, 2023). "In HNSCC cell lines, these authors demonstrated that inhibition of PIM-1 expression with siRNA induced radiosensitization of tumor cells, therefore supporting the concept that PIM-1 protects cells from radiotherapy-induced damage." (PMID 34993612, 2022).
tumor (continued). "Patients with a high PIM-1 expression value (n = 43, 31.9%) had a significantly higher rate of local tumor recurrence than patients with low expression (n = 92, 68.1%)." (PMID 34993612, 2022). "Several studies have proven the favorable efficacy and safety of VEGFR inhibitors and inhibitors of other tumor-associated targets (including EGFR, FGFR, BRAF, c-Met, HDAC, tubulin, ERα and PIM1) combination therapy in patients with tumors." (PMID 35799213, 2022). "According to our results, the transcriptional expression of PIM-1 was significantly related to the local control of the tumor in patients with HNSCC treated with radiotherapy, chemoradiotherapy, or bioradiotherapy." (PMID 34993612, 2022). "The knockdown of USP28 blunts the upregulation of PIM1 in xenograft tumor models and results in reduced tumor growth." (PMID 35326457, 2022). "In an in vivo experimental study with a murine model, it was shown that inhibition of PIM-1 led to a significant reduction in tumor growth." (PMID 34993612, 2022). "Immunohistochemical studies carried out in patients with HNSCC have found a significant increase in the expression of PIM-1 in tumor tissue, opposite to healthy mucosa." (PMID 34993612, 2022). "Patients with a local tumor recurrence had significantly higher PIM-1 transcriptional expression values than patients in which treatment with radiotherapy achieved local control of the disease (P = 0.017)." (PMID 34993612, 2022). "A recent study on circulating tumor cells in patients with metastatic castration resistant PCa reports that PIM1 is overexpressed in 37.5% of the cases." (PMID 35163481, 2022). "In the case of W390A MLV, mice 7, 11, and 12 had a dominant clone in the tumor with integrations into the Ppp1r16b, Pim1, and Notch1 oncogenes, respectively." (PMID 35852337, 2022). "Knockdown or downregulation of PIM-1 was shown to inhibit tumor proliferation and induce mitochondria-mediated apoptosis by activating caspase-9." (PMID 36687624, 2022). "Consistently, the protein levels of TRIM44, p-STAT3, BCL2, MMP9, HIF-1α and PIM1 were all decreased in SPATS2 knockdown tumor tissues, which underpinned the contribution of SPATS2-TRIM44-p-STAT3 axis to tumorigenic events in HCC." (PMID 33391405, 2021). "Of note, the use of PIM1 inhibitors or silencing of PIM1 expression in vitro resulted in a significant inhibition of the tumor cell growth through induction of apoptosis, cell cycle arrest and sensitization against chemotherapeutic agents." (PMID 34681783, 2021). "Currently available studies have suggested that PIM1 expression is correlated with the enhanced metastatic potential of the tumor and can be predictive of tumor outcome following chemotherapy and surgery." (PMID 34503111, 2021). "The molecular mechanism underlying its overexpression in pancreatic carcinomas is based on the presence of cis-acting AREs in the PIM1’s mRNA 3′ untranslated region, which mediates an interaction with HuR in a tumor hypoxia context." (PMID 34572861, 2021). "miR-486 directly targets Pim-1 and downregulated miR-486 in NSCLC leads to the overexpression of Pim-1 to promote tumor progression, suggesting that critical tumor suppressive functions of miR-486 in NSCLC." (PMID 33898432, 2021). "The change of BCL2 and PIM1 indicated the role of SPATS2-mediated p-STAT3 in HCC tumor growth, limitless replicative potential and resistance to apoptosis." (PMID 33391405, 2021). "Physcion 8-O-β-glucopyranoside represses tumor growth of hepatocellular carcinoma via downregulation of PIM1." (PMID 33842552, 2021). "Although these three PIM kinases share more than 60% homology, only PIM1 appears to have a significant impact on tumor formation." (PMID 34681783, 2021). "As shown in the volcano plot, SU decreased GZMB expression and upregulated genes related to inflammatory activation (FOS, JUN, NFKBIA, DUSP2, JAK1, PIM1), tumor immunity (CD47, PCBP2, EIF5A, PDIA3, EGR1), and DNA damage (H2AFX, DDIT3, GADD45B)." (PMID 34824394, 2021).